SMPDL3B (sphingomyelin phosphodiesterase acid like 3B)
Diseases named in the same sentence as SMPDL3B in open-access papers (continued):
Sharing a sentence is not in itself a finding about the gene and the disease.
tumor (4 papers, 2020 to 2023). "Previously, it was observed that there is a substantial association between the number of M2 macrophages in the tumor microenvironment and the high expression of SMPDL3B, and this conclusion has been verified in the clinical samples." (PMID 38813495, 2023). "The infiltration of plasma cells and M2 macrophages in the tumor microenvironment, which included M2 macrophages and drew our interest for future investigation, was shown to be directly associated with the high expression of SMPDL3B, according to preliminary findings." (PMID 38813495, 2023). "The cell cycle analysis by flow cytometry showed that after SMPDL3B knockdown, fewer tumor cells were in the S phase and more of them were in the G0/G1 phase." (PMID 38813495, 2023). "The findings demonstrated that SMPDL3B knockdown reduced the capacity of tumor cells to proliferate; in contrast, SMPDL3B overexpression increased the ability of tumor cells to proliferate." (PMID 38813495, 2023). "Next, the correlation among SMPDL3B and various tumor-infiltrating immune cells was further investigated." (PMID 38813495, 2023). "High levels of SMPDL3B expression influence tumor cell proliferation through cell cycle, invasion and migration through the production of EMT-related proteins." (PMID 38813495, 2023). "In order to determine the role that this molecular expression plays in the prognosis of GAC, this study was designed to examine the expression of SMPDL3B in several tumor tissues, including GAC." (PMID 38813495, 2023). "SMPDL3B has a strong correlation with immune cell infiltration in the tumor microenvironment of GAC, particularly the presence of M2 macrophages." (PMID 38813495, 2023). "The relative contents of 22 different types of common tumor-infiltrating lymphocytes were then examined between the SMPDL3B high expression cohort and the low expression cohort." (PMID 38813495, 2023). "The outcomes indicate that SMPDL3B predominantly influences the control of the cell cycle as well as tumor cell invasion and migration through EMT-related proteins." (PMID 38813495, 2023). "This study provides a reference for further research on SMPDL3B and its role in tumor diseases and offers some fresh concepts for the identification and GAC management." (PMID 38813495, 2023). "Additionally, by creating GAC cell lines with SMPDL3B knockdown and overexpression, we will examine the impact of the SMPDL3B gene on tumor cell activity and its potential mechanism." (PMID 38813495, 2023). "Together, it is reasonable to hypothesize that SMPDL3B influences the polarization of macrophages in the tumor microenvironment and boosts the infiltration of M2 macrophages, which ultimately contributes to the poor prognosis of GAC." (PMID 38813495, 2023). "The effects of SMPDL3B have also been demonstrated in some tumor diseases." (PMID 38813495, 2023). "Moreover, the DNA fragmentation assay in tumor tissue showed that the SMPDL3B-KO tumor had a visible increase in cell apoptosis compared to the SMPDL3B-WT tumor." (PMID 34504869, 2021). "Interestingly, after a 50:50 division of the Mannheim cohort into two groups by SMPDL3B expression, a lower expression of SMPDL3B in tumor samples correlated with a shorter OS (p = 0.005) in long-term follow-up (average follow-up time: 168 months)." (PMID 32575490, 2020). "The siRNA knockdown of SMPDL3B lead to a decrease in tumor cell migration." (PMID 32575490, 2020). "In both cohorts analyzed with qRT-PCR a significant overexpression of SMPDL3B could be seen in tumor samples compared to BPH samples (Tissue scan: 6.46× and Mannheim: 37.81×, Mann–Whitney for both p < 0.001)." (PMID 32575490, 2020). "By establishing SMPDL3B knockdown and overexpression of GAC cell lines, this study confirmed that SMPDL3B promoted tumor cell proliferation, migration, and invasion." (PMID 38813495, 2023).
tumor (continued). "Additional bioinformatics research revealed a connection between SMPDL3B and immune cell infiltration in the GAC immunological microenvironment, which enhanced tumor cell proliferation by promoting the infiltration content of M2 macrophages." (PMID 38813495, 2023). "For this purpose, tumor mRNA expression data from the TCGA-STAD were acquired and separated as 408 tumor samples into 2 groups: SMPDL3B-high and SMPDL3B-low, using the median expression of SMPDL3B as a cutoff value." (PMID 38813495, 2023). "This investigation was carried out to investigate the expression of sphingomyelin phosphodiesterase acid-like 3b (SMPDL3B) in GAC and its effects on tumor progression." (PMID 38813495, 2023). "We investigated how SMPDL3B affects various key EMT proteins (E-cadherin, ZO-1, vimentin, and MMP-9) because epithelial-mesenchymal transformation (EMT) is a significant route of tumor cell migration and invasion." (PMID 38813495, 2023).
adenocarcinoma (1 paper, 2023). A common cancer characterized by the presence of malignant glandular cells. "According to the patient-prognostic information in the TCGA-STAD dataset, the overall survival of individuals with adenocarcinoma of the gastric region was also shown to be correlated with the differential expression of SMPDL3B, and patients with high expression of this gene had a worse prognosis." (PMID 38813495, 2023).
respiratory disease (1 paper, 2023). "According to core hub, genes were analyzed by degree methods, we infer that TLR4, SMPDL3B, and NFκBIA may be important regulatory genes in calves' immune response to respiratory disease." (PMID 37180342, 2023).
SMPDL3B also shares sentences with these, for which no sentence is quoted: Alport syndrome (2 papers); breast carcinoma (2); Obesity (2); chronic kidney disease (1); diabetic retinopathy (1); ductal carcinoma (1); infectious disease (1); MRSA pneumonia (1); Myalgic Encephalomyelitis (1); ovarian carcinoma (1); periodontitis (1); stomach adenocarcinomas (1); type 2 diabetes (1).